AXL (AXL receptor tyrosine kinase)
Diseases named in the same sentence as AXL in open-access papers (continued):
Sharing a sentence is not in itself a finding about the gene and the disease.
melanoma (continued). "Other markers beyond MITF and AXL can give insight to melanoma phenotypes produced by EMT." (PMID 38426087, 2024). "In addition, corin treatment of MITFlo/AXLhi melanoma cells led to decreased AXL expression and increased histone acetylation and methylation marks in all cell lines evaluated, without affecting the MEK/ERK pathway." (PMID 38300709, 2024). "The role of AXL in melanoma migration and invasion has been demonstrated." (PMID 37370757, 2023). "The most common marker of differentiated melanoma cells is the receptor tyrosine kinase (RTK) AXL." (PMID 37370757, 2023). "AXL, a tyrosine-kinase receptor, is highly expressed in malignant melanoma." (PMID 37507910, 2023). "In response to MAPK pathway inhibition, some melanoma cells undergo transcriptional reprogramming towards a melanocytic lineage dedifferentiation cell state characterized by the expression of receptor tyrosine kinases such as AXL, PDGFRβ or NGFR." (PMID 36774337, 2023). "AXL has been primarily studied in the context of acquired resistance, with only a few reports of elevated AXL expression driving intrinsic or early resistance to targeted therapies in glioblastoma, EGFR mutation positive NSCLC, and melanoma." (PMID 37727007, 2023). "In addition to its role in melanoma invasion and migration, AXL has been shown to promote both intrinsic and acquired resistance to chemotherapeutic, immunotherapeutic, and molecularly targeted therapies both in solid and hematologic malignancies)." (PMID 37370757, 2023). "Moreover, we found significant correlations between ICOS mRNA with AXL and MITF mRNA expression in the melanoma cell lines from the GDSC (ICOS/AXL: ρ = -0.457, P = 0.008; ICOS/MITF: ρ = 0.441, P = 0.010; N = 33)." (PMID 37259155, 2023). "The discovery of AXL with established roles in promoting tumor immune evasion as the top-ranked gene provides additional evidence for D374Y DEGs or its network in shaping immunosuppressive TME in melanoma." (PMID 36588164, 2023). "In melanoma, studies have shown that AXL expression was positively correlated with WNT5A." (PMID 36646673, 2023). "Notably, when comparing SK-Mel-28 and FO-1 melanoma cells to A375 cells, which are reported to exhibit higher metastatic potential, enhanced expression levels of AXL, uPAR, and MMP2 were observed in A375 cells." (PMID 37507910, 2023). "Gas6 induces ERK signaling by interacting with AXL and promotes melanoma cell proliferation." (PMID 37265798, 2023). "Small molecule AXL inhibitors have also been proposed as new therapeutic strategies in melanoma." (PMID 35406721, 2022). "Firstly, AXL was shown to be expressed in majority of melanoma lymph node metastases." (PMID 35332208, 2022). "However, similar to other TKR important in melanoma such as AXL and EGFR, ROR2 does alter the expression of numerous proteins in melanoma and other cancers." (PMID 36127680, 2022). "Heterogeneous expression of AXL is commonly observed in melanomas." (PMID 35740696, 2022). "The present study showed that in vitro, the fairy chemical ICA inhibits the expression of immune checkpoint molecules and Axl receptor tyrosine kinase in melanoma cells and that in vivo ICA improves the therapeutic response to cisplatin in mouse melanoma xenografts." (PMID 35159184, 2022). "This AXL targeting antibody conjugated to MMAE was evaluated in AXL-high mouse models of melanoma and lung cancer and found to produce an inflammatory microenvironment characterised by an influx of T cells with a skew to lymphocytes with a memory-like phenotype (CD137-high)." (PMID 36046842, 2022). "Interestingly, treatment of SKMEL28-YAP5SA cells with high doses of UFH or the LMWH nadroparin efficiently suppressed ERBB3 and AXL activity, comparably to loss of SLC35B2, further supporting HS dependency of ERBB3 and AXL signaling in melanoma cells." (PMID 35798875, 2022).
melanoma (continued). "Shedding of several RTKs, especially AXL, has been shown in patients with breast cancer and melanoma, and their circulating levels exhibited variable reduction in patients with melanoma after treatment with a combination of the MEK inhibitor trametinib and the BRAF inhibitor dabrafenib." (PMID 36358725, 2022). "Finally, we discuss about the role of cMet, AXL and Fra1, a cluster of proteins highly expressed in melanoma and involved in signaling." (PMID 35163570, 2022). "Indeed, many RTKs, including cMet and AXL, are overexpressed in malignancy, displaying oncogenic promotion of cancer progression and metastatic disease, so that high cMet expression in melanoma samples has been correlated with a poor clinical outcome." (PMID 35163570, 2022). "The upregulation of AXL occurred predominantly in the transitory and dedifferentiated melanomas, suggesting that although MITF and AXL expression has been reported to be inversely correlated in melanoma, their regulation by TNFα appear dependent on variable mediators." (PMID 34073253, 2021). "Our current findings, along with our previous discovery that the AXL/AKT axis mediates resistance to BRAF inhibition in melanoma with wild-type PTEN, provide new insights toward a strategy for combating BRAF inhibition-acquired resistance in BRAF mutant melanoma with different PTEN statuses." (PMID 34282258, 2021). "Interestingly, MITF was negatively correlated with AXL post TNFα in the dedifferentiated melanoma subtype." (PMID 34073253, 2021). "Drug cocktails containing AXL inhibitor can promote melanoma cell elimination by MAPK inhibition." (PMID 34924562, 2021). "Moreover, when the levels of both BRN2 and MITF are reduced in human melanoma cell lines, the level of AXL mRNA is induced." (PMID 34140478, 2021). "Furthermore, sAXL levels were related to the percentage of cells expressing AXL in resected melanoma lymph node metastases." (PMID 35008245, 2021). "Furthermore, we showed that sAXL levels were related to the percentage of cells expressing AXL in resected melanoma lymph node metastases." (PMID 31917795, 2020). "Together, these data demonstrated the potential of measuring sAXL in blood as a non-invasive method to monitor cellular AXL levels and showed that sAXL may be used to predict disease progression in melanoma patients." (PMID 31917795, 2020). "We hypothesized that AXL upregulation would result in AKT activation also in our melanoma transformation model." (PMID 32605315, 2020). "However, AXL has been shown to have a dual regulatory function on melanoma cell invasion, given that both inhibition or overexpression enhance invadopodia formation and activity, due to compensatory mechanisms by ERBB3 signaling pathway." (PMID 33203881, 2020). "It has been reported that MAPK inhibitor-resistant SK-MEL-28 cells have a decreased expression ratio of melanocyte-inducing transcription factor (MITF) to AXL receptor tyrosine kinase, a marker of targeted therapy resistance in melanoma, which is possibly driven by increased ATF4 expression." (PMID 33396632, 2020). "ST3GAL1 induces AXL dimerization and activation that, in turn, promotes melanoma invasion." (PMID 33203881, 2020). "In addition, biochemical and functional studies reveal that the receptor tyrosine kinase AXL is a major mediator of the pro-invasive effects of ST3GAL1 in melanoma." (PMID 33203881, 2020). "Importantly, we observed a significant decrease in H3K4me3 enrichment at the melanoma-associated genes, CD271, AXL, SOX10, and MITF." (PMID 32620791, 2020). "Next, we checked whether the expression of AXL, a marker of melanoma metastasis recently connected with drug resistance, was also increased in resistant melanoma cell lines obtained in this study." (PMID 31936151, 2020).
melanoma (continued). "Accumulating evidence indicate that AXL is a marker of invasive phenotype in melanoma, linked to the absence of microphthalmia-associated transcription factor (MITF) and the expression of an EMT signature." (PMID 33203881, 2020). "Furthermore, protein levels of GLI1, SOX2, ST3GAL1, and AXL were analyzed in short-term cultures of primary and metastatic melanomas." (PMID 33203881, 2020). "Consequently, combination of MEKi trametinib and AXL inhibitor R428 synergistically reduced tumour growth and metastasis in orthotopic TNBC (and melanoma) xenograft models derived from cell lines that showed increased surface AXL following MEKi." (PMID 35582276, 2019). "In comparing IL32 expressing and non-expressing melanoma cell lines, we observed that IL32 expression in melanoma cell lines correlates with a high AXL/low MITF ratio, a genetic signature which has been reported to be associated with a treatment-resistant, dedifferentiation “invasive” phenotype." (PMID 30953519, 2019). "In addition, either high MIFT-levels or a low MIFT/AXL-ratio were shown to be associated with resistance of BRAF-and NRAS-mutant melanoma cells towards kinase inhibitors and other targeted therapies." (PMID 29794999, 2018). "In melanoma, the balance of master regulator microphthalmia-associated transcription factor (MITF) and tyrosine kinase AXL has been shown to function as rheostat determining the transition between proliferative and invasive state—with highest MITF levels promoting neuronal differentiation." (PMID 29794999, 2018). "In addition, EGFR-STAT3, CDK2 and AXL/AKT signaling pathways play critical roles in BRAFi resistance in melanoma." (PMID 30400954, 2018). "For melanoma cell lines, the preeminent factors are the presence of the most significantly mutated genes (BRAF, NRAS, NF1, or triple wild type) and proliferative or invasive behavior (MITF/AXL expression ratio)." (PMID 29383127, 2017). "We could further confirm the mutual exclusion of MITF/EDNRB and AXL/EDNRA expression in a panel of melanoma cell lines." (PMID 28606996, 2017). "In addition, we sought to identify melanoma cell lines that are better models of their tumour counterparts while accounting for MITF or AXL enriched transcriptional states." (PMID 28060736, 2017). "There is a strong rationale for targeting MET, AXL, and VEGFRs in melanoma." (PMID 28103611, 2017). "In addition, we found co-expression of RUNX2 and another RTK, AXL, in both melanoma cells and melanoma patient samples." (PMID 27102439, 2016). "Low levels of MITF and high levels of AXL may predict melanoma resistance to BRAFi, and the resistance may involve (re)activation of MAPK or PI3K/mTOR signaling." (PMID 26918352, 2016). "In addition, AXL promotes the pro-migratory and pro-invasive behavior of melanoma cells and resistance to the BRAF V600E inhibitor PLX4720." (PMID 27102439, 2016). "Moreover, AXL expression correlates with drug resistance in patients with melanoma, myeloid leukemia, lung cancer, and renal cell carcinoma." (PMID 27834845, 2016). "Finally, we showed a dramatic up regulation of RUNX2 expression with concomitant up-regulation of EGFR, IGF-1R and AXL in melanoma cells resistant to the BRAF V600E inhibitor PLX4720." (PMID 27102439, 2016). "In addition, we found high levels of phosphorylated EGFR (Y1068) and phosphorylated AXL (Y702) in C8161 melanoma cells, in contrast to C81-61 melanoma cells." (PMID 27102439, 2016). "However, as shown in CCLE dataset and by drug sensitivity assays on melanoma cell lines, melanomas with high expression of AXL include both resistant and sensitive tumors." (PMID 25742786, 2015). "Indeed, we have previously shown that AXL is highly expressed, at the protein level, in human melanoma cell lines and clinical samples which lacks expression of MITF and of MITF-targets." (PMID 25742786, 2015). "In melanoma, AXL is activated and preferentially expressed in melanoma lacking MITF." (PMID 24344100, 2013).
melanoma (continued). "Two plastic phenotypic states have been described in melanoma: a proliferative state driven by micropthalmia-associated transcription factor (MITF) and an invasive state linked to upregulation of the tyrosine protein kinase receptor AXL, which is involved in epithelial-mesenchymal transition (EMT)." (PMID 40537707, 2025). "AXL mRNA is a direct target of miR-34a-5p in lung cancer, showing that the overexpression of miR-34a-5p suppresses AXL expression and inhibits cell migration and invasion in triple-negative breast cancer, leading to reduced proliferation and invasion, and other cancers, including melanoma." (PMID 40869968, 2025). "Thus, as a tyrosine kinase receptor, AXL functionally plays an essential role in different oncogenic processes in addition to its suppressive activity, which leads to the destruction of cell death machinery in melanoma." (PMID 37370757, 2023). "Several genes implicated in melanoma FA metabolism have been reported to correlate with the expression of MITF, a hallmark marker of the “proliferative to invasive” phenotype switch, or of AXL, another hallmark marker of a de-differentiated and drug-resistant phenotype." (PMID 35912092, 2022). "However, quantification of sAXL blood levels is a simple and easily assessable method to determine cellular AXL levels that could be further evaluated for use as a biomarker of disease progression and treatment response in melanoma." (PMID 35008245, 2021). "In addition to expression of AXL, NGFR and a lineage-specific transcription factor MITF, expression of SOX transcription factors that are associated with control of cancer cell plasticity, is broadly used to classify the phenotypes of melanoma cells." (PMID 31936151, 2020). "Finally, it may be reasonable to develop CAR-T cells targeting proteins highly expressed in dedifferentiated melanoma, such as AXL, whose expression is clearly inversely correlated with that of MITF." (PMID 33276788, 2020). "Furthermore, we observed a correlation between cellular AXL expression and sAXL levels in melanoma cell lines and patient samples, suggesting that measuring sAXL may be used as an easy assessable marker to determine disease progression and aggressiveness." (PMID 31917795, 2020). "In addition, single-cell expression analyses identified melanoma cells with a low MITF/AXL ratio in MITF-high bulk melanomas, which may be able to evade senescence and confer treatment resistance." (PMID 30651597, 2019). "Furthermore cells cultured at 5 mM glucose increase the levels of the tyrosine kinase receptor AXL, a marker for melanoma cells with a more invasive phenotype, and indeed glucose restriction significantly increases melanoma cell invasiveness through collagen I 3D-matrices." (PMID 28380427, 2017). "Indeed, AXL+/WNT5A+ melanoma cells are resistant to MAPK pathway inhibitors and this might, at least in part, be due to the fact that the regulation of MITF expression is disconnected from BRAF." (PMID 25818589, 2015). "Our study describes a novel ERK5/KLF4/AXL signaling axis that drives MEKi resistance and metastatic potential in NRAS-mutant melanoma and highlights this axis as a potential target to improve MAPK-directed and potentially immune therapies." (PMID 41916083, 2026). "In melanoma, ST3GAL1 enhances dimerization and activation of the receptor tyrosine kinase AXL, increasing invasion and metastatic seeding." (PMID 41416421, 2026). "Resistance to BRAF inhibition (BRAFi) is a significant clinical obstacle, as certain melanoma cells can downregulate key regulators of melanocyte differentiation, such as MITF, and upregulate RTKs like AXL and EGFR." (PMID 40386826, 2025).
melanoma (continued). "The most consistent candidate drug treatments for invasive melanoma were glucocorticoid receptor (NR3C1) agonists, AXL inhibitors, PARP1 inhibitors and HDAC inhibitors, as target gene expression for drug families predicted to target invasive melanoma." (PMID 38183207, 2025). "Other genes such as NR3C1, AXL, PARP1 and several HDAC genes were consistently found in invasive melanoma." (PMID 38183207, 2025). "Although significant modulation of mRNA levels was observed only in LM-20, Western blot analyses showed that the transfection of miRNA mimics resulted in a significant reduction in AXL and FRA1 protein expression across all three melanoma cell lines." (PMID 40869968, 2025). "Previous studies have found glucocorticoid receptor agonism, AXL inhibition and HDAC inhibition can overcome treatment resistance in melanoma." (PMID 38183207, 2025). "Similar to the increase of FRA1 in melanoma cells compared to wildtype or BRAF-mutant melanocytes, AXL, CDK6, and Fascin levels are increased in melanoma cells, especially in cells exhibiting high levels of FRA1." (PMID 41286309, 2025). "Therapeutically, targeting pathways that sustain this reprogramming, particularly the AXL/YAP, IL-6/gp130, and COX-2–PGE2 axes, represent a promising approach to reduce melanoma adaptability and improve long-term treatment outcomes." (PMID 41465101, 2025). "Collectively, these results complement the existing models based on the dynamic interplay of known melanoma lineage-defining transcription factors like MITF, SOX10, BRN2, and AXL, by adding KPC1 as a crucial checkpoint." (PMID 41429767, 2025). "For example, AXL and FRA1 are two emerging potential targets that are overexpressed in melanoma and are important in several signaling regulator pathways involved in melanoma progression and metastasis." (PMID 40869968, 2025). "In preclinical studies using a melanoma model, the activity of an AXL-directed ADC was potentiated by combination with MAPK inhibitors, which also suggests a potential role for AXL-directed therapy in combination with other targeted therapies." (PMID 41166388, 2025). "Comprehensive multi-omics integration revealed transcriptional target genes of FRA1, with AXL, CDK6, and FSCN1 exhibiting increased expression in melanoma metastasis and a significant correlation with poor patient outcomes." (PMID 41286309, 2025). "On transcriptome level, SK-Mel-28 dr cells showed elevated AXL and reduced MITF expression, representing a trend towards an AXLhigh/MITFlow phenotype, which defines a dedifferentiated melanoma phenotype." (PMID 39835134, 2024). "•AXL+ and/or MITF+ melanoma subpopulations were analyzed by NanoString, scRNAseq and multiplex immunofluorescence." (PMID 39697983, 2024). "Our observation of lower proportions of MITF+ melanoma cells in patients’ metastatic lesions taken after immunotherapy compared to pre-therapy supports the hypothesis of a more efficient targeting of these cells by therapy-induced immune response, while AXL+ melanoma cells may be more resistant." (PMID 39697983, 2024). "Based on transcriptomic data, the AXL and MITF subpopulations have been identified in melanoma and play a major role in tumor heterogeneity, as shown in our and other’s data." (PMID 39697983, 2024). "In line, GRASLND is inversely correlated with RTK AXL, having a Spearman coefficient of −0.80 (p = 1.8 × 10−8), supporting our findings of a correlation between GRASLND expression and the melanoma cell state." (PMID 39398277, 2024). "Recent studies in male melanoma and male breast cancer (MBC) have identified significant roles played by the androgen receptor (AR) and AXL in cancer progression and prognosis." (PMID 39597836, 2024). "A375 cells are acknowledged to be a particularly invasive and aggressive type of melanoma that is MITF-negative and AXL-enriched." (PMID 39596498, 2024).